GNA13 (G protein subunit alpha 13)
Description:
Guanine nucleotide-binding proteins (G proteins) are involved as modulators or transducers in various transmembrane signaling systems. Activates effector molecule RhoA by binding and activating RhoGEFs (ARHGEF1/p115RhoGEF, ARHGEF11/PDZ-RhoGEF and ARHGEF12/LARG). GNA13-dependent Rho signaling subsequently regulates transcription factor AP-1 (activating protein-1) (By similarity). Promotes tumor cell invasion and metastasis by activating RhoA/ROCK signaling pathway. Inhibits CDH1-mediated cell adhesion in a process independent from Rho activation. In lymphoid follicles, transmits P2RY8- and S1PR2-dependent signals that lead to inhibition of germinal center (GC) B cell growth and migration outside the GC niche.
Synonyms: G13; MGC46138; HG1N
Tractability: Small molecule: a structure with a bound ligand is known. Antibody: UniProt places it where antibodies can reach, with high confidence; its Gene Ontology location is reachable by antibodies, with high confidence. PROTAC: ubiquitination databases record sites on it; its protein half-life has been measured.
Gene: Protein-coding gene on chromosome 17 (65,009,289 to 65,056,817, reverse strand). Ensembl gene ENSG00000120063.
Subcellular location: Cell membrane; Melanosome; Cytoplasm; Nucleus
Subcellular location (Human Protein Atlas): Cytosol
Pathways (Reactome):
Signal Transduction: CDC42 GTPase cycle; G alpha (12/13) signalling events; NRAGE signals death through JNK; RAC1 GTPase cycle
Hemostasis: Thrombin signalling through proteinase activated receptors (PARs); Thromboxane signalling through TP receptor
Gene Ontology:
Molecular function: G protein activity; protein binding; D5 dopamine receptor binding; G-protein beta/gamma-subunit complex binding; GTPase activity; guanyl-nucleotide exchange factor activity; G protein-coupled receptor binding; guanyl nucleotide binding
Biological process: Rho-activating G protein-coupled receptor signaling pathway; adenylate cyclase-activating G protein-coupled receptor signaling pathway; adenylate cyclase-modulating G protein-coupled receptor signaling pathway; regulation of small GTPase mediated signal transduction; Rho protein signal transduction; signal transduction; G protein-coupled receptor signaling pathway; regulation of blood pressure; regulation of postsynapse assembly
Cellular component: cytoplasm; cytoplasmic side of plasma membrane; cytosol; extracellular exosome; focal adhesion; membrane; nucleus; brush border membrane; plasma membrane; melanosome; postsynapse
Genetic constraint (gnomAD): Loss-of-function variants: 2 observed, 24.05 expected, observed/expected ratio (o/e) 0.0832, 90% interval 0.033 to 0.26. The upper end of that interval is the gene's LOEUF score, 0.26, which puts it in group 1 of 6, group 1 being the genes least tolerant of losing a copy. Missense variants: 274 observed, 438.2 expected, observed/expected ratio (o/e) 0.63, 90% interval 0.57 to 0.69. Synonymous variants: 159 observed, 168.39 expected, observed/expected ratio (o/e) 0.94, 90% interval 0.83 to 1.08.
Homologues: Orthologues: chimpanzee GNA13 (99% identical), macaque GNA13 (99% identical), pig GNA13 (98% identical), rabbit GNA13 (97% identical), rat Gna13 (97% identical), guinea pig GNA13 (97% identical), mouse Gna13 (97% identical), tropical clawed frog gna13 (90% identical), zebrafish gna13a (86% identical), zebrafish gna13b (84% identical), Drosophila melanogaster cta (55% identical), Caenorhabditis elegans gpa-12 (46% identical), and 16 more. Paralogues in human: GNA12 (63% identical), GNA11 (45% identical), GNAQ (45% identical), GNA14 (44% identical), GNAO1 (41% identical), GNA15 (40% identical), GNAI2 (40% identical), GNAI1 (39% identical), GNAI3 (38% identical), GNAL (38% identical), GNAS (38% identical), GNAT1 (38% identical), and 3 more.
Diseases named in the same sentence as GNA13 in open-access papers:
GNA13 is named in the same sentence as 52 diseases in open-access papers, as found by Europe PMC text mining. Sharing a sentence is not in itself a finding about the gene and the disease. The quoted sentences say what the papers report.
breast carcinoma (12 papers, 2015 to 2024). "GNA13 mutations are present at a high frequency in gastric cancer, nasopharyngeal cancer, prostate cancer, breast cancer, lymphoma, and bladder cancer." (PMID 35237598, 2022). "Taken together, our data indicates that loss of miR-31 in breast cancers leads to increased GNA13 expression and cancer cell invasion." (PMID 25889182, 2015). "Loss of miR-31 expression and increased GNA13 expression could be used as biomarkers of breast cancer progression." (PMID 25889182, 2015). "In this study we find that GNA13 regulates the expression of MYC exclusively in ER+ breast cancer cells, and that the induction of MYC observed upon GNA13 loss is dependent on the expression and activation of ERα." (PMID 38965558, 2024). "Further enrichment analysis of the RNA-seq data using Gene Ontology was carried out to identify the biological processes and cellular components impacted by manipulation of GNA13 expression in these ER+ breast cancer cells." (PMID 38965558, 2024). "We first examined the correlation between GNA13 expression (TCGA) and overall survival in breast cancer using KMplotter." (PMID 38965558, 2024). "Several proteins involved in this pathway are associated with breast cancer prognosis (including ERCC6 and POSTN34,35) and/or sensitivity/resistance to endocrine or other chemotherapy (including EGFR, ABL1, GNA13, and PTK736–39)." (PMID 39030258, 2024). "The expression of GNA13 in breast cancer cells is primarily regulated by MicroRNA (miR)-31, and the absence of miR-31 increases the expression of GNA13 and the invasion of cancer cells." (PMID 35237598, 2022). "MiR-31 has already been shown to have anti-metastatic properties for breast cancers via targeting GNA13 and WAVE3." (PMID 27926494, 2017). "In the current study, we found that breast cancer cells depend on GNA13 protein expression, for optimal cell invasion." (PMID 25889182, 2015). "All of the data presented to date are consistent with the notion that the GNA13-3′-UTR is a target of miR-31 activity in breast cancer cells." (PMID 25889182, 2015). "Our data demonstrate that GNA13 is an important mediator of cancer cell invasion, and that its expression is regulated by microRNA-31 in breast cancer cells." (PMID 25889182, 2015). "Expression analysis of miRNAs predicted to bind the 3′-UTR of GNA13 revealed that miR-31 exhibited an inverse correlation to GNA13 protein expression in breast cancer cells." (PMID 25889182, 2015). "Examination of 48 human breast cancer tissues revealed that GNA13 mRNA levels were inversely correlated to miR-31 levels." (PMID 25889182, 2015). "Similar to that observed previously in prostate cancer cell lines, examination of a panel of breast cancer cell lines revealed that GNA13 levels are greatest in more invasive cell lines such as MDA-MB-231 and MDA-MB-157." (PMID 25889182, 2015). "The data presented above provide compelling evidence that miR-31 directly binds to GNA13 mRNA, and that this binding impacts both GNA13 expression and breast cancer cell invasion." (PMID 25889182, 2015). "A screen for microRNAs that are predicted to target GNA13 in breast cancer cells revealed that miR-31 shows an inverse correlation to GNA13 protein expression in these cells." (PMID 25889182, 2015). "Importantly, we observed that PERP, ITB1, GNAS2, and GNA13 are upregulated by trastuzumab in ErbB2-positive human breast cancer cells BT-474 and MCF-7/Her2-18 which indicates that the effect of trastuzumab on these proteins is not unique to one cell line." (PMID 33023655, 2020). "Previous data suggested that GNA13 was significantly upregulated in more aggressive breast cancer cells, and elevated GNA13 expression might be used as a potential marker for breast cancer progression." (PMID 27883022, 2016). "Interestingly, however, miR-31 showed a clear inverse correlation to GNA13 protein expression in the breast cancer cells." (PMID 25889182, 2015).
breast carcinoma (continued). "This project was carried out to determine (i) whether enhanced GNA13 expression is important for breast cancer cell invasion, and (ii) if so, the mechanism of deregulation of GNA13 expression in breast cancers." (PMID 25889182, 2015). "Additionally our data shows that miR-31 regulates breast cancer cell invasion partially via targeting GNA13 expression in breast cancer cells." (PMID 25889182, 2015). "Importantly a screen for miR-31 and GNA13 expression showed a significant inverse correlation of these two transcripts in breast cancer tissues." (PMID 25889182, 2015). "Furthermore, it was found that miR-194-5p was enriched with lncRNA-HEIH and that miR-194-5p reduced the levels of lncRNA-HEIH and GNA13, which are involved in the metastatic potential of breast cancer and may serve as a prognostic biomarker for HCC patients." (PMID 38297160, 2024). "To obtain evidence for which, if any, of the potential regulatory miRNAs might be impacting GNA13 expression in breast cancer cells, we performed a comparison of GNA13 protein levels (by immunoblot analysis) and of the respective miRNAs (by real time PCR), respectively." (PMID 25889182, 2015). "However, little is known about the control of GNA13 expression in breast cancers." (PMID 25889182, 2015). "Given our recent findings that GNA13 expression is regulated via post-transcriptional mechanisms in prostate cancer cells by miRNAs, we were curious as to whether similar mechanisms might be involved in control of expression of GNA13 in breast cancer cells." (PMID 25889182, 2015). "Understanding the specific role of GNA13 in breast cancer cell invasion and the mechanism of its regulation could lead to the development of novel strategies to inhibit cancer invasion and metastasis in breast cancers using microRNAs." (PMID 25889182, 2015). "Another study showed that enhanced signaling involving the oncogene GNA13 downregulates KLK5 gene transcription, which promotes breast cancer progression." (PMID 38090381, 2023). "BRD4/LSD1/NuRD complex then represses the activation of drug-resistant genes such as WNT4, LRP5, BRAF, GNA13, and PDPK1 in breast cancer cells." (PMID 35740532, 2022). "Our study indicates that levels of proteins PERP, GNAS2, GNA13, ITB1, and RAB10 in EVs emitted by cultured breast cancer cells correlate with sensitivity of these cells to trastuzumab." (PMID 33023655, 2020). "Other potential biomarkers of breast cancer trastuzumab response are proteins GNAS2, GNA13, RAB10, and ITB1 that we discovered via proteomics-based analysis." (PMID 33023655, 2020). "For example, one of the cell lines in our breast cancer screen, MDA-MB-436, had relatively low expression of GNA13 even though this cell line is derived from metastatic breast cancer." (PMID 25889182, 2015). "This activates GNA13 and PDPK1 expression leading to drug resistance in breast cancer." (PMID 35740532, 2022). "In summary, we have demonstrated that trastuzumab upregulates PERP, ITB1, GNAS2, and GNA13 in EVs emitted by two different trastuzumab-sensitive breast cancer cell lines but not in EVs derived from two different trastuzumab-resistant breast cancer cell lines." (PMID 33023655, 2020). "We also noticed that trastuzumab upregulates ITB1, GNAS2, and GNA13 in EVs emitted by trastuzumab-sensitive breast cancer cells MCF7/Her2-18, but not in EVs emitted by ErbB2-positive trastuzumab-resistant human breast cancer cells HCC-1419." (PMID 33023655, 2020). "Taken together, these data indicate that GNA13 is an important regulator of breast cancer cell invasion, but not cell proliferation." (PMID 25889182, 2015). "Surprisingly, unlike prostate cancer cells, GNA13 expression in breast cancer cells is mainly regulated through miR-31 and not through miR-182 and miR-200a." (PMID 25889182, 2015).
breast carcinoma (continued). "Interestingly, high GNA13 expression significantly correlated with better survival rates in all breast cancer patients regardless of treatment group, in patients who underwent treatments other than endocrine therapy, in ER+ patients who underwent endocrine therapy and also in ER- patients." (PMID 38965558, 2024). "Our data indicate that PERP, GNA13, GNAS2, ITB1, and RAB10 are upregulated in EVs derived from trastuzumab-sensitive but not from trastuzumab-resistant breast cancer cells in culture." (PMID 33023655, 2020). "Interestingly, unlike the case with EVs, trastuzumab did not upregulate all of the indicated proteins in the breast cancer cells themselves: the drug upregulated RAB10 and PERP in BT-474 cells but downregulated ITB1 and did not change the levels of GNAS2 and GNA13 in the cells." (PMID 33023655, 2020).
prostate carcinoma (8 papers, 2014 to 2025). A carcinoma that arises from epithelial cells of the prostate gland. "Similar results were observed in other human cancers, such as small cell lung cancer and prostate cancer, in which the increased expression of GNA13 was associated with malignant phenotypes or inferior prognosis." (PMID 26735177, 2016). "In the same study we reported that GNA13 was upregulated in aggressive prostate cancer cells and this upregulation was mediated by loss of microRNAs, specifically by miR-182 and miR-200a, in a synergistic fashion." (PMID 25889182, 2015). "Furthermore, while there are no activating mutations of GNA13 in androgen-independent metastatic prostate cancer, gene amplification of wild-type GNA13 is seen in 4.4% (19/429) of cases." (PMID 40430023, 2025). "Recently, however, we showed that loss of wild type GNA13 alone could inhibit invasion and migration in vitro significantly in prostate cancer cells." (PMID 25889182, 2015). "Silencing of GNA13 increased mitochondrial superoxide levels when prostate cancer cells were cultured in galactose medium and increased the sensitivity to oxidative metabolic stress when the cells were cultured in media containing non-glycolytic metabolites." (PMID 40430023, 2025). "We recently showed that GNA13 is highly expressed in aggressive breast and prostate cancer cell lines, and that blocking GNA13 expression is sufficient to block cancer cell invasion." (PMID 29255247, 2018). "GNA13 overexpression also drives an aggressive phenotype in human small cell lung cancer and prostate cancer cells and enhances mouse xenograft tumor growth in vivo." (PMID 26735177, 2016). "Our recent study showed that control of GNA13 expression by specific microRNAs (miRNAs or miRs) is important for prostate cancer cell invasion." (PMID 25889182, 2015). "Additionally, deregulation of miRNAs has been closely associated with oncogenesis and tumor progression in several cancer types, In the context of GNA13 regulation, we have reported that miR-182 and miR-200a are involved in control of GNA13 expression in prostate cancer cells." (PMID 25889182, 2015). "Silencing of c-Jun expression reduced mRNA and protein levels of GNA12, but not the closely-related GNA13, in prostate cancer cells." (PMID 28394299, 2017).
B-cell lymphoma (7 papers, 2018 to 2025). "Concordantly, recurrent inactivating mutations in the G-protein superfamily gene GNA13 have been described in B cell lymphomas, and the contribution of nitric oxide to apoptosis resistance in CLL cells has been addressed by various studies." (PMID 31142279, 2019). "Mutations in GNA13 and RHOA have been reported in Burkitt's lymphoma and diffuse large B–cell lymphoma, in which they promote B–cell lymphoma development." (PMID 41362935, 2025). "By negatively regulating the expression of BCL2, GNA13 has also been identified as a tumor suppressor in B-cell lymphoma." (PMID 37759431, 2023). "Previous studies suggest that GNA13, which is related to cell migration, is the most common mutant gene in germinal center (GC)-derived B-cell lymphoma, including nearly a quarter of Burkitt’s lymphoma and GC-derived diffuse large B-cell lymphoma cases." (PMID 34925435, 2021). "Moreover, expression of GNA13WT but not the palmitoylation-defective form of GNA13 inhibited proliferation of B-cell lymphoma, suggesting that palmitoylation of GNA13 is required for its tumor suppression function." (PMID 37759431, 2023).
Burkitt lymphoma (7 papers, 2021 to 2025). A rare form of malignant mature B-cell non-Hodgkin lymphoma. "Recent mutational cartography efforts in Burkitt lymphoma identified additional recurrent mutations in GNA13, RET, PIK3R1, DDX3X, FBXO11, and the SWI/SNF genes ARID1A and SMARCA4." (PMID 34283060, 2021). "Additionally, loss of function GNA13 mutations are enriched in Burkitt lymphoma (BL), which is defined by MYC translocations and commonly presents with mLN involvement." (PMID 39025963, 2024). "GNA13 variants are mostly heterozygous, including nonsense, frameshift, and missense mutations, like the mutation patterns in DLBCL and Burkitt’s lymphoma." (PMID 35237598, 2022). "In malignant tumors of the hematopoietic and lymphatic system, GNA13 and RhoA mutations are present in B-cell lymphomas, mainly in DLBCL and Burkitt’s lymphoma." (PMID 35237598, 2022). "Mutations of GNA13 have been found in about 18% in GCB-DLBCL, 13% Burkitt lymphoma (BL), and 15.6% Follicular Lymphoma (FL), respectively, including multiple point mutations and truncated variants." (PMID 33423045, 2021).
gastric cancer (6 papers, 2016 to 2022). A primary or metastatic malignant neoplasm involving the stomach. "Studies have showed that overexpression of GNA13 is associated with increased proliferation and tumorigenicity of gastric cancer cells through the upregulation of c-Myc, activation of AKT, and activity of the ERK signaling pathway." (PMID 33396517, 2020). "We reported that GNA13 was upregulated in gastric cancer(GC), and GNA13 upregulation was closely associated with aggressive characteristic of cancer progression and poor survival in GC patients." (PMID 27883022, 2016). "In this study, GNA13 was characterized for its role in gastric cancer (GC) progression and underlying molecular mechanisms." (PMID 26735177, 2016). "A recent study confirmed these findings and showed that GNA13 expression is a potential biomarker for poor survival in gastric cancers." (PMID 29255247, 2018). "GNA13 is also a biomarker for the prognosis and metastasis of solid tumors, including HNSCC, ovarian cancer, lung cancer, and gastric cancer." (PMID 35237598, 2022). "We previously observed that upregulation of GNA13 could promote the tumorigenicity and proliferation of gastric cancer(GC) cells." (PMID 27883022, 2016).
lymphoma (6 papers, 2016 to 2021). A malignant (clonal) proliferation of B- lymphocytes or T- lymphocytes which involves the lymph nodes, bone marrow and/or extranodal sites. "And GNA13 loss is associated with GC B-cell persistence, which may lead to an increased risk of lymphoma development." (PMID 34925435, 2021). "In contrast to us, Muppidi JR reported GNA13 signaling is frequently disrupted in germinal center B cell-derived lymphoma, and exerts dual actions in suppressing growth and blocking dissemination of germinal center B cells." (PMID 26735177, 2016). "Conditional knock-out alleles have been successfully employed to study the in vivo role of many lymphoma-associated tumor suppressor genes encoding for transcription factors (BLIMP1), epigenetic modifiers (EZH2, CREBBP, KMT2D, TET2), small G proteins (GNA13) and ubiquitin ligases (FBXO11)." (PMID 34456919, 2021). "We also found SWI mutations in GNAI2 (p.R179), in skin melanoma and lymphomas, where it has oncogenic effects by upregulating ERK1/2, and in GNA13 (p.R200; in bladder carcinoma), which is not yet fully understood." (PMID 31337866, 2019).